Y_RNA (Y RNA )
Gene: Miscellaneous RNA gene on chromosome 4 (145,149,537 to 145,149,649, reverse strand). Ensembl gene ENSG00000238713.
Homologues: Orthologues: chimpanzee Y_RNA (99% identical). Paralogues in human: RNY1 (90% identical), Y_RNA (90% identical), Y_RNA (88% identical), RNY1P11 (87% identical), Y_RNA (87% identical), Y_RNA (86% identical), Y_RNA (85% identical), Y_RNA (84% identical), RNY1P7 (83% identical), RNY1P8 (83% identical), Y_RNA (83% identical), Y_RNA (82% identical), and 99 more.